PROS1 (protein S)
Diseases named in the same sentence as PROS1 in open-access papers (continued):
Sharing a sentence is not in itself a finding about the gene and the disease.
COVID-19 (76 papers, 2020 to 2025). A disease caused by infection with severe acute respiratory syndrome coronavirus 2. "SARS-CoV-2 can directly activate the complement system via all three complement pathways, and single-nucleotide variants of complement C4BP-α, which interacts with PROS1, are risk factors for morbidity and death in COVID-19." (PMID 40980495, 2025). "In parallel, PROS1 reduced myeloid phenotypes associated with severe COVID-19, while supporting a phenotype with efficient antigen presentation." (PMID 40980495, 2025). "Hypercoagulable states, heritable coagulopathies (e.g., factor V Leiden mutation, protein S deficiency, and antiphospholipid syndrome), infectious etiologies (e.g., sepsis, COVID-19), and solid tumor malignancies are all known to contribute to TAMT." (PMID 38910702, 2024). "Recently, protein S1 (PROS1) has been described to be involved in the occurrence of coagulopathies associated with COVID-19." (PMID 38398746, 2024). "It was reported that plasminogen and plasmin contribute to susceptibility to COVID-19 and that in vitro experiments revealed that plasmin cleaves protein S of SARS-CoV allowing it to penetrate the cellular host." (PMID 37037462, 2023). "There is scarcity of data on the association of Protein S activity with COVID-19 and systemic sclerosis." (PMID 36577976, 2022). "It has already been suggested that loss of protein S is associated with a loss of crucial immune inhibition that has detrimental effects on COVID-19 severity." (PMID 35111793, 2021). "What is more, the understanding of mutations and their impact on the stability of protein S structure may contribute to the development of prevention and treatment strategies for COVID-19." (PMID 40732754, 2025). "Early assessment of PROS1 levels may contribute to reducing the incidence of COVID-19-associated cardiovascular events, particularly in LCS cases, by facilitating the early identification of the most susceptible patients." (PMID 38398746, 2024). "To date, the mechanism underlying the alteration of the coagulation cascade in COVID-19 patients remains misunderstood and the anticoagulant protein S (PROS1) has been described as a potential risk factor for complications related to COVID-19, due to PLpro SARS-CoV-2 enzyme proteolysis." (PMID 38398746, 2024). "They found that protein S activity was lower in patients with COVID-19, and its level was associated with disease severity and mortality, suggesting that it may have a role in the thromboembolism associated with COVID-19 infection." (PMID 36845330, 2023). "Prediction, structure analysis, experimental affinity, and clinical studies of patients with severe COVID-19 have indicated that some ACE2 polymorphisms have a higher affinity for protein S. During SARS-CoV-2 infection, severe inflammation favors the expression of ACE2 and TLR-4." (PMID 35062298, 2022). "The modest protein S deficiency manifested by the patient has been hypothesized to contribute to cytokine storm in COVID-19 and could be the result of exuberant dysregulated blood coagulation." (PMID 33560944, 2021). "Because both hypoxia and IL6-induced inflammation depress Protein S abundance, it’s reasonable to consider administration of Protein S as an effective therapy in severe Covid19 patients." (PMID 32826388, 2020). "Most importantly, protein S, a vitamin K-dependent glycoprotein, not only has a major role in the anti-coagulation pathway, but also prevents the production of inflammatory cytokines associated with the cytokine storm observed in acute lung, liver and heart injury seen in COVID-19 patients." (PMID 36014944, 2022). "Besides PtdSer, it was speculated that PROS1 might mechanically associate excessive blood coagulation with immune response in COVID-19." (PMID 35033201, 2022).
COVID-19 (continued). "So far overlooked is the fact that both IL6 and hypoxia depress the abundance of a key anticoagulant, Protein S. We speculate that the IL6-driven cytokine explosion plus hypoxemia causes a severe drop in Protein S level that exacerbates the thrombotic risk in COVID-19 patients." (PMID 32826388, 2020). "We previously found higher expression of protein S (PROS1) in lung epithelium of mild compared to severe coronavirus disease 2019 (COVID-19) patients." (PMID 40980495, 2025). "Monitoring altered plasmatic levels of PROS1 or incorporating its assessment during therapy could aid in identifying COVID-19 subjects at higher risk for PROS1-associated coagulopathies, which can significantly exacerbate the clinical course in COVID-19 patients." (PMID 38398746, 2024). "The impact of SARS-CoV-2 on PROS1 activity has been substantiated through the observation of reduced activity in 65% of COVID-19 patients." (PMID 38398746, 2024). "Another group of researchers, in addition to a decrease in protein S in patients hospitalized with a diagnosis of COVID-19, observed a decrease in protein C, a decrease in factor XII, and a decrease in antithrombin activity." (PMID 39457048, 2024). "While the specific role of PROS1 in SARS-CoV-2 coagulopathies is an area of ongoing research, its potential involvement in the context of COVID-19-associated clotting disorders is noteworthy." (PMID 38398746, 2024). "Patients with severe COVID-19 are characterized by increased activity of the coagulation system and suppression of the fibrinolytic system and the protein C–protein S—thrombomodulin system in blood plasma." (PMID 39457048, 2024). "Considering this, assessing PROS1 plasmatic levels and CD147 expression emerges as a potent diagnostic and therapeutic tool for COVID-19 patients, providing insights into the risk for SARS-CoV-2-associated coagulopathies." (PMID 38398746, 2024). "To conclude, the admission levels of protein C and protein S activities are decreased in COVID-19-infected patients when compared to the healthy population." (PMID 36845330, 2023). "Significantly higher levels of free protein S were found in the HCs (94.06 ± 8.945%) compared to mild COVID-19 patients (46.35 ± 16.85, p < 0.001), moderate COVID-19 patients (61.55 ± 26.18%, p < 0.01), and severe COVID-19 patients (54.00 ± 20.84, p < 0.001)." (PMID 36982991, 2023). "Extraction of neutralizing antibodies from COVID-19 patient serum verified the strong immunogenicity of complete protein S, the receptor binding domain (RBD) and N-terminal domains (NTD) being also immunogenic." (PMID 36679885, 2022). "Less than 5% of nasal epithelial cells from patients with COVID-19 expressed PROS1 compared with healthy controls." (PMID 36560757, 2022). "Increased thrombotic factors (such as decreased protein S) and decreased fibrinolytic activity due to increased PAI-1 were potential factors causing thrombogenesis after COVID-19 vaccination." (PMID 35999558, 2022). "Our data shows that severe COVID-19 patients had decreased plasma levels of Protein S, suggesting it is rapidly being consumed, and increased PAI-1, which is a direct manifestation of endothelial cell dysfunction." (PMID 34341659, 2021). "The latest evidence on VK and pulmonary disease stem from the fact that VK can activate protein S, which was recently shown to prevent the generation of inflammatory cytokines and cytokine storms detected in COVID-19 cases." (PMID 33917442, 2021). "Low protein S levels were correlated lately with higher thrombogenicity, clinical severity, and fatal outcome in COVID-19 patients, independently of age or even Inflammatory biomarkers." (PMID 33917442, 2021). "The reduced activation of protein S due to the pneumonia-induced vitamin K depletion was correlated with higher thrombogenicity and possibly fatal outcomes in COVID-19 patients." (PMID 33917442, 2021).
COVID-19 (continued). "In contrast, COVID-19 patients with milder respiratory distress were characterized by increased plasma levels of the inflammation-resolving, antithrombotic cytokine PROS1, which characterized the resident AM FABP4+ cluster." (PMID 34143756, 2021). "We investigated the persistence of increased plasma SPP1, S100A12, GAS6, and PROS1 into the SARS-CoV-2– post–COVID-19 phase, often characterized by complex pathologies." (PMID 34143756, 2021). "High factor VIII, von Willebrand factor levels, and low protein S levels have been consistently reported in patients with COVID-19, but their role in the pathogenesis is unclear." (PMID 34476137, 2021). "Low levels of protein S, due to pneumonia-induced VK depletion, were correlated with higher thrombogenicity and possibly fatal outcomes in COVID-19 patients." (PMID 33917442, 2021). "AM from healthy lungs showed high expression levels of AXL and PROS1, and these were markedly reduced in patients with severe COVID-19." (PMID 34143756, 2021). "In contrast, stimulation with protein S showed a significantly higher activation of SARS-CoV-2 specific T cells in patients with mild compared to patients with critical COVID-19 as well as between patients with severe and critical disease progression (right)." (PMID 34194438, 2021). "Consistent with scRNAseq data, plasma Protein S levels were higher in COVID-19 patients who maintained lung functions (i.e., sustained PaO2/FiO2 > 200), suggesting a potential role in counterbalancing the severity of inflammation of SARS-CoV-2 infection." (PMID 34143756, 2021). "The scRNAseq data show that, in healthy human BALF, the FABP4+ macrophages express the TAM receptor AXL and the ligand for the TAM receptor MerTK (PROS1) and that these were profoundly repressed in severe COVID-19." (PMID 34143756, 2021). "Recent research shows that protein S, another vitamin K-dependent protein, can prevent the cytokine storm observed in COVID-19 cases." (PMID 33917442, 2021). "An optimum plasma PROS1 cut-off value was calculated at 15 μg/mL, above which 34.1% of COVID-19 patients had severe respiratory distress as compared with 59% of those with PROS1 < 15 μg/mL." (PMID 34143756, 2021). "Of note, dexamethasone, which has been approved as COVID-19 treatment for seriously ill patients, is a potent activator of the PROS1/MERTK axis." (PMID 32998369, 2020). "Nonetheless, before Protein S administration can be deemed a new therapeutic approach, it is necessary to determine the extent to which Protein S is downregulated in a large cohort of COVID-19 patients." (PMID 32826388, 2020). "In summary, these results suggest that local higher levels of PROS1 characterizing mild COVID-19 might contribute to the reduced proinflammatory response and enhanced repair of the epithelial barrier in those patients." (PMID 40980495, 2025). "Hypothesizing that PROS1 protects against severe COVID-19, in this study, we aimed to investigate the mechanisms by which PROS1 could modulate the epithelial and monocyte responses toward SARS-CoV-2 infection." (PMID 40980495, 2025). "Specifically, a notable absence is the evaluation of plasma PROS1 activity, which could significantly enhance our comprehension of PROS1’s physiological and pathological functionality in individuals with COVID-19." (PMID 38398746, 2024). "Given the increasing focus on cardiovascular long-term effects of COVID-19, this study seeks to elucidate the potential connection between alterations in PROS1 plasma levels and the concomitant presence of the virus within cardiovascular tissues, following past or ongoing SARS-CoV-2 infection." (PMID 38398746, 2024). "Thus, this study aimed to assess serum protein C and protein S levels at the time of COVID-19 diagnosis and their relation to infection severity." (PMID 36845330, 2023). "Furthermore, there is evidence that activation of the NF-kB inflammatory pathway in COVID-19 (a disease aggravating factor) by protein S is dependent on TLR2 signaling." (PMID 37895256, 2023).
COVID-19 (continued). "Moreover, about 70% of the COVID-19 patients (25/36) displayed lower values of free protein S, i.e., below the threshold of the normal range (<65%)." (PMID 36982991, 2023). "Low protein S levels, often due to pneumonia-induced vitamin K depletion, were correlated lately with higher thrombogenicity, clinical severity, and fatal outcome in COVID-19 patients, independently of age or inflammatory biomarkers." (PMID 36014944, 2022). "However, and with regard to patient security, a special insight should be performed on the presence of COVID-19’s mRNA or derived proteins (protein S) even inactivated within the donor tissues." (PMID 33397467, 2021). "S100A12 and PROS1 were unrelated to age in COVID-19 and in SARS-CoV-2– pneumonia." (PMID 34143756, 2021). "In addition, differences in Th cell activation were only detected against protein S of SARS-CoV-2 revealing lowest T cell activation in patients with critical COVID-19 (right)." (PMID 34194438, 2021). "A substantial number of severe COVID-19 patients manifest both hypoxia and prothrombotic complications and we speculate that reduced Protein S level might play a key role in the disease progression of these patients." (PMID 32826388, 2020). "The immune response following COVID-19 vaccination involves two processes: cellular response—which generates diverse T-cell lineages, interferons, and interleukins—and the generation of IgG antibodies that target viral antigens, including protein S, triggered by the first process." (PMID 37242357, 2023). "Moreover, CTSB is involved in the entry of the COVID-19 virus within cells via the endosomal pathway by cleaving and activating protein S. Additionally, expression of CTSB in COVID-19 may also lead to an increased risk of COVID-19 infection." (PMID 37037462, 2023). "Thus, it is expected that vaccinated people present anti-protein S antibodies, while people with previous COVID-19 may present anti-protein S and anti-nucleoprotein antibodies." (PMID 35214613, 2022). "PROS1-induced reduction of epithelial-driven inflammation and promotion of epithelial barrier repair, combined with reduction of myeloid-driven coagulation and complement pathways and efficient antigen presentation, may all combine to determine a mild COVID-19 phenotype." (PMID 40980495, 2025). "This demonstrated the importance of PROS1 in modulating epithelial-derived phenotypes and mediators of SARS-CoV-2 infection, thus modulating the severity of COVID-19." (PMID 40980495, 2025). "Sequential measurement of platelet indices, TAT, PAP, protein C, protein S, vWF, D-dimer, and PAI-1 following COVID-19 vaccination was informative." (PMID 35999558, 2022). "There are also similarities between LD subjects and severe COVID-19 subjects with KNG (pro coagulation-platelet degranulation), LRG1 (antimicrobial), and PROS1 (anticoagulant), which are found in higher abundance in both." (PMID 36569838, 2022). "In COVID-19 cases, the reduced activation of MGP and protein S due to the pneumonia-induced VK depletion can lead to an escalation in pulmonary injury and thrombosis." (PMID 33917442, 2021). "However, the reduced PROS1, which is the preferred activating ligand for MerTK, and the fewer homeostatic resident AMs in severe COVID-19 might enable unrestricted proinflammatory cytokine production by locally differentiated MerTK-expressing FCN+ and FCN+SPP1+ macrophages." (PMID 34143756, 2021). "Protein S (PROS1), an anticoagulant and anti-inflammatory mediator, was elevated at the mRNA level in the ciliated epithelial cells specifically in mild COVID-19 cases, but not in severe cases." (PMID 40980495, 2025).
COVID-19 (continued). "PROS1 is an agonist for tyrosine kinase receptors MERTK and TYRO3, through which it limits the activation of innate immune responses, vascular permeability, response to cell damage, and coagulation-related pathologies in COVID-19." (PMID 40980495, 2025). "Therefore, the modification of PROS1 expression by PLpro within platelets could disturb thrombin formation and activate platelets, potentially contributing to the disruption of various platelet functions observed in COVID-19 patients, playing a role in the formation of thrombi." (PMID 38398746, 2024). "In our study we did not estimate the levels of Antithrombin III, Protein C, and Protein S by immunological and coagulological methods since we have dealt with acute thrombosis triggered by COVID-19." (PMID 36980916, 2023). "That is why it was proposed that ACE2 polymorphisms could also contribute to susceptibility to SARS-CoV-2 infection, affecting the interaction of protein S with ACE2 and the COVID-19 severity." (PMID 35062298, 2022). "Next, we investigated whether concomitant pharmacological drug treatment, demographic factors (age and sex), and COVID-19 comorbidities contributed to the plasma levels of SPP1, S100A12, GAS6, and PROS1." (PMID 34143756, 2021). "There is a possibility that the ELISA method underestimates galectin-3 concentrations in COVID-19 positive patients, which could be because the SARS-CoV-2 protein S contains a domain that is practically homologous to this lectin." (PMID 34205807, 2021). "The dysregulation of blood coagulation during COVID-19 results in depleted circulating PROS1 levels, which can consequently contribute to cytokine storm by reducing the immunosuppressive action of MERTK in macrophages and diminishing intrinsic PROS1 anticoagulant function." (PMID 40980495, 2025). "Here, we demonstrated that while routine coagulation blood testing (d-dimer, free protein S and fibrinogen) could distinguish between COVID-19 patients and HCs, these tests were not able to distinguish between the three levels of clinical COVID-19 patients’ disease severity." (PMID 36982991, 2023).
breast carcinoma (55 papers, 1990 to 2026). "The immune-related vitamin K-dependent glycoprotein encoded by PROS1 is synthesized in the liver and is a tumor suppressor that can inhibit metastasis by suppressing the TNF-alpha pathway in lung and breast cancers." (PMID 37063858, 2023). "In addition to ProS1, Gas6 was also found to be strongly expressed in particular cancer cell types, with the highest levels in MDA-MB-231 breast cancer cells." (PMID 31766614, 2019). "Finally, while AXL has been the main TAM family member that has been investigated in breast cancer, future work should also consider the role of other TAM family members, especially given the demonstrated cross-talk between these receptors and the recent finding that protein S can stimulate AXL." (PMID 32148495, 2020).